MMP1 (matrix metallopeptidase 1)
Diseases named in the same sentence as MMP1 in open-access papers (continued):
Sharing a sentence is not in itself a finding about the gene and the disease.
aneurysm (10 papers, 2014 to 2024). Bulging or ballooning in an area of an artery secondary to arterial wall weakening. "Upregulation of both MMP-2 and MMP-9, as well as of MMP-1, has been reported in aneurysms of the abdominal aorta." (PMID 39408865, 2024). "In patients with aneurysms of TAA, increased circulating levels of MMP-1, -2 and TIMP-1 were reported and were also associated with the shear stress which, in turn, promotes aortic structure remodeling and consequently favors aneurysm expansion." (PMID 33573220, 2021). "It is possible that the elevation of MMP1 may reflect inflammatory conditions at the site of the aneurysms." (PMID 27418197, 2016). "This work implicates interaction of MMP-9 and MMP-1 with aneurysm formation in Kawasaki disease." (PMID 25191698, 2014). "Specifically, an overexpression of MMP-1, -2, and -9 has been observed in aneurysm walls, with higher levels of MMP-2 and -9 found in ruptured aneurysms." (PMID 39301423, 2024). "For example, the ratio MMP1:TIMP1 mRNAs, which differed between segments (from 0.85 in the proximal part, nearly doubled (1.65) in aneurysm sac and 1.1 in the distal segment) could be a result of dysregulation of their expression in the segments." (PMID 34091862, 2021). "Moreover, only moderate correlation (rS = 0.41) was found between the relative expression of MMP1 and TIMP1 along the aneurysm tissue." (PMID 34091862, 2021). "We found only a significantly lower mRNA expression of MMP-2 in aneurysms, whereas higher expression of MMP-9 in aneurysms was not significant between the groups as well as the expression of MMP-1 and MMP-14." (PMID 26539497, 2015).
cervical squamous cell carcinoma (10 papers, 2021 to 2025). A squamous cell carcinoma arising from the cervical epithelium. "In cervical squamous cell carcinoma, high expressed MMP1 was associated with poor prognosis and negatively related to the amount of T cells and macrophages infiltration." (PMID 35426219, 2022). "Notably, the expression of MMP1 is inversely associated with the infiltration of T cells and macrophages in cervical squamous cell carcinoma." (PMID 38580797, 2024). "Studies carried out on cervical squamous cell carcinoma showed that MMP1 is inversely related to CD4, CD8, and macrophage activity in the tumor microenvironment." (PMID 35083113, 2022). "We found that MMP1 gene alterations were most frequent (> 8%) in cervical squamous cell carcinoma among all tumors, and the predominant type of alterations was amplification." (PMID 36727076, 2022). "MMP1 might be a biomarker for immunotherapy and prognostic judgment in cervical squamous cell carcinoma." (PMID 35426219, 2022).
myocardial infarction (10 papers, 2013 to 2024). Gross necrosis of the myocardium, as a result of interruption of the blood supply to the area, as in coronary thrombosis. "Recent studies have shown an association of MMP1 levels with a wide variety of disorders, including polycystic kidney disease, rheumatoid arthritis, idiopathic pulmonary fibrosis, congestive heart failure, and acute myocardial infarction." (PMID 23497408, 2013). "Meanwhile, recent studies showed that a variety of MMPs increase in the myocardium after myocardial infarction, including MMP-1, MMP-2, MMP-3, MMP-7, MMP-9, MMP-11, and so on." (PMID 25237357, 2014). "Furthermore, acute myocardial infarction reperfusion significantly alters MMP-1 levels over time." (PMID 39877021, 2024). "Elevated MMP-1 levels in myocardial infarction patients, without corresponding increases in TIMP-1, correlate with poorer ventricular function." (PMID 39877021, 2024).
Sepsis (10 papers, 2010 to 2025). Sepsis is defined as life-threatening organ dysfunction caused by a dysregulated host response to infection. "A second result of the present study is the association between sepsis caused by intracellular pathogens and MMP-1 rs1799750 G insertion." (PMID 35204780, 2022). "Among patients with sepsis, carriers of MMP1 rs1799750 G/G have an increased susceptibility for intracellular pathogen infections, while virus serology is more often positive in those with the MMP3 rs3025058 A/A genotype." (PMID 35204780, 2022). "Some of the MMPs laterly increased in plasma, such as MMP-1, lead to sepsis-associated clotting abnormalities." (PMID 24833564, 2014). "We report here for the first time an association between the MMP-13 (−77 A/G) and the MMP-1 (−1607 1G/2G) SNPs and sepsis." (PMID 24833564, 2014). "Genetic variants in loci of MMP-1 or -3 promoters binding NF-kB or ets transcription factors could therefore increase susceptibility to sepsis." (PMID 35204780, 2022). "The association of MMP-1 with sepsis has been recently reported." (PMID 24833564, 2014). "We report for the first time an association between MMP-13 and MMP-1 SNPs and sepsis." (PMID 24833564, 2014). "The association of the MMP-1 (-1607 1G/2G) SNP and sepsis might be due to linkage disequilibrium with the MMP-13 SNP because the MMP-13 and MMP-1 genes are both located in the same cluster of the chromosome 11q22-23 along with the MMP-3, MMP-7, MMP-8, MMP-10, MMP-12, and MMP-20 genes." (PMID 24833564, 2014). "GPs of MMPs and TIMP (namely MMP-1 rs1799750, MMP-3 rs3025058, MMP-8 rs11225395, MMP-9 rs2234681, and TIMP-1 rs4898) have been compared in 1058 patients with suspected sepsis to assess the association with susceptibility and etiology of sepsis." (PMID 35204780, 2022). "Other studies have identified other MMP variants as associated with sepsis susceptibility or prognosis: MMP-1, MMP-3, MMP-8, and TIMP-1 variants have already been investigated in sepsis outcome in a few hundred ICU patients with severe sepsis." (PMID 35204780, 2022). "Increased levels of active MMP-1 have been associated with lower rates of survival in patients with sepsis, while mouse models show MMP-1 inhibitors prevent sepsis- induced lethality." (PMID 30466423, 2018). "MMP-9, TIMP-2 and TIMP-1 have been shown to be elevated in patients with severe sepsis and septic shock as well as in animal models of endotoxemia, while MMP-1, MMP-8 and MMP-13 have also been associated with sepsis." (PMID 30466423, 2018). "Gelatinases (MMP-2 and -9) have been related to sepsis so far although less attention has been paid to collagenases (MMP-1, - 13) and stromelysins (MMP-3, -10)." (PMID 24833564, 2014). "In conclusion, we report for the first time an association between the MMP-13 and the MMP-1 SNPs and sepsis, as well as an independent association of plasma MMP-8 and MMP-9 levels with sepsis." (PMID 24833564, 2014). "In addition to their role in tumor progression, elevated MMP1 levels can disrupt endothelial barriers, contributing to inflammatory responses and tissue damage, as observed in conditions like sepsis and potentially in CRS." (PMID 40004863, 2025). "MMP-1 is expressed by unstressed endothelial cells and secreted by these cells in sepsis." (PMID 24833564, 2014). "Co-incubation of human renal epithelial cells with iMS1 cells resulted in the up-regulation of MMP1, an important regulator of tissue remodeling and extracellular matrix homeostasis that has been previously shown to be up-regulated during the development of sepsis." (PMID 34103408, 2021). "Among the MMPs showing earlier increased plasma levels in sepsis were MMP-3, -8, and -10 as we observed while others like MMP-1 and -9 increased later." (PMID 24833564, 2014). "In conclusion, the current analysis stresses the relevance of MMP-1, -2, -7, -13 and sE-selectin concentrations for the transition of SIRS to sepsis." (PMID 20165718, 2010).
Sepsis (continued). "In this study, we demonstrate the relevance of MMP-1, -2, -7, -13 and sE-selectin for the distinction between SIRS and sepsis." (PMID 20165718, 2010). "The present study reports the associations between MMP-8 rs11225395 G/G genotype and sepsis compared to patients without sepsis and, moreover, of the MMP-1 rs1799750 and MMP-3 rs3025058 genotypes with diagnosis of sepsis due to intracellular pathogens or virus, respectively." (PMID 35204780, 2022). "We bring forward now the potential role of collagenases (MMP-13 and MMP-1) and perhaps stromelysins (MMP-3) in sepsis, an interesting finding because these MMPs are neither expressed in neutrophils nor released from neutrophils granules after endotoxin challenge as MMP-8 and MMP-9 do5." (PMID 24833564, 2014).
skin cancer (10 papers, 2006 to 2025). "Acute and chronic exposure of the skin to UV irradiation induces MMP-1 expression and causes DNA damage, ultimately leading to premature skin aging (photoaging) and skin cancer." (PMID 29570674, 2018). "Thus, interindividual variation in antioxidant abilities in the epidermis may also cause interindividual variation in the expression of MMP-1 triggered by chronic sun exposure, resulting in interindividual variation in skin cancer risks." (PMID 40094840, 2025). "This oxidative stress accelerates matrix metalloproteinases (MMPs) production, (especially MMP1), leading to collagen and elastin degradation in human skin, implicating sunlight as a major factor in photoaging and even skin cancer." (PMID 40227287, 2025). "We identify that the same inflammatory myofibroblast phenotype (IL11+MMP1+CXCL8+IL7R+) can be observed in early human skin wounds, skin cancer and inflammatory skin diseases with scarring risk." (PMID 40993240, 2025). "Our article indicated that people with mutations in the genes FokI (rs2228570), ERCC2 (rs13181), MMP1 (rs475007), and ERCC2 (rs238406) were more likely to have skin cancer." (PMID 36874118, 2023). "Because monocyte-derived M2 macrophages produce MMP1 and MMP25 by RANKL stimulation, TAMs in skin cancer of apocrine origin produce MMP1 and MMP25 at the tumor site." (PMID 29410946, 2018). "MMP1 over-expression was also observed in dermal fibroblasts from xeroderma pigmentosum group C patients and is thought to be involved in skin cancer development in these patients." (PMID 19287498, 2009). "In addition to skin cancer, MMP-1 may be involved in the pathogenesis of other diseases; however, there are currently no confirmed reports on this matter." (PMID 40094840, 2025). "Tsukifuji and colleagues reported an over-expression of MMP-1, MMP-2, and MMP-3 in skin cancer (16 Ak, 6 AK with SCC, and 15 SCC)." (PMID 16893473, 2006). "We detected an increased expression rate of MMP-1 and MMP-9 in skin cancer and both genes showed the highest expression rate in AK/SCC indicated by the change-folds of MMP-1 (<10), and MMP-9 (4.70) by microarray analysis." (PMID 16893473, 2006). "Samples of perilesional skin and different skin tumors (viral warts and different stages of cSCC) were analyzed for hyperactivation of the MEK-ERK pathway by staining for pERK1/2, activation of epidermal MMP1 and MMP3 expression, as well as stromal upregulation of GM-CSF." (PMID 35174094, 2022).
chronic obstructive pulmonary disease (9 papers, 2009 to 2021). A chronic and progressive lung disorder characterized by the loss of elasticity of the bronchial tree and the air sacs, destruction of the air sacs wall, thickening of the bronchial wall, and mucous accumulation in the bronchial tree. "Mutations in MMP1 are associated with chronic obstructive pulmonary disease." (PMID 34587931, 2021). "The chronic obstructive pulmonary disease (COPD)-predisposing variant P19S enhances the activity of MMP-1 by increasing TRPV4 activation." (PMID 33803491, 2021). "Like MMP1 and MMP3, its common polymorphisms have been linked to chronic obstructive pulmonary disease, cardiovascular disease, and some cancers." (PMID 25111588, 2015). "MMP-1 and -7 may be diagnostic biomarkers that distinguish IPF from other chronic lung diseases such as chronic obstructive pulmonary disease and sarcoidosis." (PMID 26415518, 2015).
triple-negative breast carcinoma (9 papers, 2011 to 2025). An invasive breast carcinoma which is negative for expression of estrogen receptor (ER), progesterone receptor (PR), and human epidermal growth factor receptor 2 (HER2). "Overexpression of MMP1 is associated with tumor invasion and metastasis and is highly expressed in triple-negative breast cancer." (PMID 38283944, 2023). "Our findings show a significant difference in MMP-1 positivity of cancer associated stromal cells between luminal A, luminal B and triple-negative breast cancer types." (PMID 21835023, 2011). "A significant difference of MMP-1 expression by cancer associated stromal cells in luminal A, luminal B and triple-negative breast cancer classes was also demonstrated." (PMID 21835023, 2011). "In triple-negative breast cancer tissues, MMP1 protein expression positively depended on lymph node metastasis; furthermore, in an in vitro study, knockdown of MMP1 inhibited cell proliferation in triple-negative breast cancer MBA-231 cells." (PMID 35037689, 2022). "Recently, the up-regulation expression of MMP1 was observed during human triple negative breast cancer cell line progression to lymph node metastasis in a xenografted model in nude mice, indicating potential targets involved in the control of metastasis." (PMID 23951052, 2013). "MMP-1 expression in stromal cells showed a significant association with luminal A and luminal B, HER2 overexpressing and triple-negative breast cancer subtypes." (PMID 21835023, 2011). "In luminal B subtype, the MMP-1 expression in stromal cells was higher than in luminal A subtype (p = 0.0258), and also the luminal B subtype stromal cells showed higher MMP-1 positivity than triple-negative breast cancer cells (p = 0.0336)." (PMID 21835023, 2011). "Furthermore, with the aid of transcriptomic analysis and ChIP-qRT-PCR assay, we identified that RUNX2/MMP1 axis functioned a crucial role in the malignant progression and poor prognosis in triple negative breast cancer." (PMID 36483054, 2022). "MMP1 might play a critical role in mediating the tumor-promoting effect of RUNX2 in triple negative breast cancer cells." (PMID 36483054, 2022). "Furthermore, with the aid of transcriptomic and bioinformatic analyses, we found MMP1 was highly expressed in triple negative breast cancer (TNBC) and showed a strong correlation with the poor prognosis of the patients, which was consistent with the expression pattern of RUNX2." (PMID 36483054, 2022). "In triple-negative breast cancer, PRDX3 regulates tumor metastasis via ERK signaling-mediated MMP-1 expression." (PMID 41049446, 2025). "Inhibition of MLK3 downregulated the expression of FRA-1, MMP-1 and MMP-9, leading to the transendothelial migration and matrigel invasion of triple-negative breast cancer cells." (PMID 33407478, 2021). "To further illustrate the molecular mechanism of MMP1 and RUNX2 in TNBC, we initially examined the expression pattern of RUNX2 and MMP1 in the SUM-149 and MDA-MB-231 triple negative breast cancer cell line and the MCF-7 non-triple negative breast cancer cell line." (PMID 36483054, 2022). "Consistently, we found that the mRNA expression levels of RUNX2 and MMP1 revealed similar expression pattern, and in particular, those in triple negative breast cancer cell line were significantly higher than in non-triple negative breast cancer cell line." (PMID 36483054, 2022).
Alzheimer disease (8 papers, 2012 to 2024). A progressive, neurodegenerative disease characterized by loss of function and death of nerve cells in several areas of the brain leading to loss of cognitive function such as memory and language. "Patients with Alzheimer’s disease have increased levels of fibronectin and decreased levels of MMP-1, which may be associated with impaired cognitive functions." (PMID 36362588, 2022). "MMP-1 levels in glial cells have been shown to be increased in Alzheimer’s disease pathology." (PMID 30873018, 2019). "Several SASP factors, including IL-6, IL-1β, TNF-α, MMP-1, MMP-3, and MMP-10, have also been found to be elevated in the cerebrospinal fluid and serum of patients with Alzheimer’s disease." (PMID 37569663, 2023).
cardiac hypertrophy (8 papers, 2012 to 2022). "Clinical studies have shown that myocardial TIMP-1 and TIMP-2 mRNA expression is increased in patients with aortic stenosis, and myocardial MMP-1 and TIMP-1 protein expression is increased in patients with myocardial hypertrophy." (PMID 25861361, 2015). "In fact, an experimental study has shown that paricalcitol attenuated the cardiac hypertrophy and fibrosis, by reducing collagen I, TGF-β1 and increasing MMP1, an interstitial collagenase that degrades type I, II, and III structural collagens, favoring the reduction of collagen." (PMID 33401711, 2021). "However, since we did not detect MMP-1 in cardiomyocytes, the development of cardiac hypertrophy in EMMPRIN knockout mice might differ from that in isolated cardiomyocytes." (PMID 33400052, 2021).
disc degeneration (8 papers, 2009 to 2025). "Another study analysing the bony and soft tissue surgical specimens of patients with AS and degenerative disc disease found elevated cathepsin K and MMP1, which have been implicated in bone resorption and cartilage tissue destruction." (PMID 38405075, 2024). "Historically, the matrix metalloproteinases, including MMP-1, -2, -3, -7, -8, -9, -13, -19 and -28, have been considered the key players in disc matrix destruction during disc degeneration." (PMID 21880134, 2011). "We also investigated the degree of deformity and its impact on the production of MMP-1, as well as the possible aetiopathogenic role of this mechanism in disc degeneration and progression of the scoliotic curve." (PMID 21554726, 2011). "The proportion of MMP-1 decreases with advancing disc degeneration, and both enzymes are equally expressed in the most degenerative IVD." (PMID 19906289, 2009). "Although the association between adult disc degeneration and MMPs has previously been reported, the expression of MMP-1 in scoliotic intervertebral discs in a growing spine has not been studied yet." (PMID 21554726, 2011). "For example, one study demonstrated that leptin promotes catabolic activity in rat NPCs by upregulating the expression of MMP‐1, MMP‐13, ADAMTS4, and ADAMTS5 via activation of the JAK2/STAT3 pathway, suggesting a mechanism contributing to disc degeneration." (PMID 41497807, 2025). "Analysis from mouse NP tissues shows sufficient quantities of RNAs, purity of the NP fraction, and overall RNA quality for gene expression studies, and reveals no increase in expression of disc degeneration markers, including TNFa, IL1b, and Mmp1 up to 15 months of age in C57BL6 wildtype mice." (PMID 31891122, 2019).
esophageal cancer (8 papers, 2010 to 2025). A primary or metastatic malignant neoplasm involving the esophagus. "In esophageal cancer, TGF-β, MMP-1, and CXCR4 were upregulated and associated with cancer progression." (PMID 24130695, 2013). "This blockade led to reduced expression of IL-19-regulated genes such as TGF-β, Matrix Metalloproteinase-1 (MMP-1), CXCR4, and Cyclin B (CCNB1), highlighting the therapeutic potential of IL-19 inhibition in esophageal cancer." (PMID 40806452, 2025). "MMPs such as MMP-1 and MMP-2 were found to be important in proliferation, invasion, and migration of esophageal cancer cells." (PMID 24130695, 2013). "Expression of MMP-1 and -13 was analyzed in esophageal cancer (n = 41 EAC with BE, n = 19 EAC without BE, and n = 10 esophageal squamous-cell carcinomas, ESCC), furthermore in BE without intraepithelial neoplasia (IN) (n = 18), and the cell line OE-33." (PMID 20946664, 2010).